SEMA3G (semaphorin 3G)
Diseases named in the same sentence as SEMA3G in open-access papers (continued):
Sharing a sentence is not in itself a finding about the gene and the disease.
tumor (continued). "In conclusion, we have found for the first time that the semaphorins sema3A, sema3D, sema3E and sema3G possess anti-tumorigenic and anti-angiogenic properties similar to those displayed by the previously identified tumor suppressor sema3F." (PMID 18818766, 2008). "In contrast, the np2 agonist sema3G was unable to inhibit tumor development from these cells, although it was highly expressed as compared to sema3D." (PMID 18818766, 2008). "Regarding SEMA3G, a recently identified semaphorin, no data have been published to our knowledge about its function in tumours." (PMID 18781179, 2008). "These previous papers indicate the role of aberrant SEMA3G in tumor biology." (PMID 40533501, 2025). "Notably, SEMA3G overexpression in the tumor microenvironment resulted in a reduction in tumor size and a marked increase in survival duration." (PMID 40533501, 2025). "Similarly, recombinant SEMA3G significantly suppressed the tumor growth and prolonged the survival time." (PMID 40533501, 2025). "Finally, we determined the correlation of SEMA3G expression with tumor immune infiltration level, biomarkers of immune cells or immune checkpoint levels in KIRC." (PMID 38070142, 2023). "Furthermore, we also confirmed significant correlation of SEMA3G expression with tumor immune infiltration levels, expression of biomarkers of immune cells or immune checkpoints in KIRC." (PMID 38070142, 2023). "Little is known about the roles of sema3D and sema3G in tumor progression." (PMID 30696103, 2019). "Interestingly, three of the ligands with reduced expression in high PC3a and low PC4a samples, SEMA3B, SEMA3F, and SEMA3G, had both anti-angiogenic and tumor suppressor functions." (PMID 23667446, 2013). "We also determined whether sema3D, sema3F and sema3G, which inhibit tumor formation from MDA-MB-435 cells, also inhibit the anchorage free growth of these cells." (PMID 18818766, 2008). "However, a comprehensive investigation regarding the expression, role, mechanism and the association between SEMA3G and tumor immune infiltration is still absent." (PMID 38070142, 2023). "Lower mRNA expression of SEMA3B, SEMA3D, SEMA3G, and PLXNA2 or higher mRNA expression of SEMA3F, NRP1, ITGB3, ITGA5, and VEGFA genes were detected in the older patient group and associated with the higher tumor grade, wild-type status of IDH, and lower rate of survival time (p < 0.05)." (PMID 33036421, 2020). "In contrast, expression of sema3A did not inhibit tumor development, while sema3D which binds to both neuropilins, significantly inhibited tumor development from the MDA-MB-435 cells though less potently than sema3G which may be due to the lower expression levels obtained with sema3D in these cells." (PMID 18818766, 2008). "Our study identifies SEMA3G as an important EC-derived signal that directly impairs GSC stemness and inhibits GSC-originated tumor growth in mice." (PMID 40533501, 2025). "Among them, we selected seven genes associated to cell proliferation and apoptosis that resulted downregulated in tumor samples: BTG1, CCNG1, DMD, EDG1, SEMA3G, SYNPO2, TIMP2." (PMID 39984959, 2025). "Next, we generated alkaline phosphatase-tagged (AP-tagged) recombinant SEMA3G-AP and revealed the direct binding of SEMA3G-AP to GBM tumor tissues." (PMID 40533501, 2025). "Considering the close relationship of SEMA3G with tumor immune infiltration in KIRC, we further assessed the correlation of SEMA3G expression with the levels of immune checkpoints (PD-1, PD-L1 and CTLA4)." (PMID 38070142, 2023). "Therefore, SEMA3G might be a potential tumor suppressor and favorable prognostic biomarker in KIRC." (PMID 38070142, 2023). "A prognostic index for tumor samples could be calculated by the formula: IRGPI = (HTN3 expression * 0.096) + (CTSG expression * −0.152) + (MAPT expression * 0.122) + (CCL28 expression * −0.094) + (PTX3 expression * 0.138) + (SEMA3G expression * −0.140) + (USP2 expression * 0.107)." (PMID 36845378, 2023).
tumor (continued). "Next, we conducted bioinformatics analysis on SEMA3G, and data from TCGA-KIRC database (normal: 72, tumor: 539) showed that the expression level of SEMA3G in ccRCC tissues was remarkably lowerthan that in normal tissues." (PMID 36882799, 2023). "Whereas SEMA3A, SEMA3C, and SEMA3F were mainly up-regulated in the tested tumours, the rest of the members SEMA3B, SEMA3D, SEMA3E and SEMA3G were primarily down-regulated with a few exceptions." (PMID 32241267, 2020). "In relation to the malignancy grade of the tumor, mRNA levels of SEMA3B, SEMA3C, SEMA3D, SEMA3G, PLXNA2, and CDH1 decreased while mRNA levels of SEMA3F, NRP1, ITGB3, ITGA5, and VEGFA increased with the increase of the tumor malignancy (p < 0.05)." (PMID 33036421, 2020). "All other SEMA3 family members show inconsistent up- or down-regulation in different cancer tumours, where SEMA3B, SEMA3D, SEMA3E, and SEMA3G are primarily down-regulated, and SEMA3A and SEMA3C are mainly up-regulated in the tested cancer types." (PMID 32241267, 2020). "In the case of VEGFA, SEMA5A, and SEMA3G, the expression levels in the MSL subtype were closer to those of normal tissues than the tumor average." (PMID 23667446, 2013). "With the exception of sema3G and sema3B, expression of these semaphorins in U87MG cells inhibited significantly tumor development from subcutaneously implanted cells." (PMID 22936999, 2012). "In this work, we firstly conducted pan-cancer expression and survival bioinformatic analysis for SEMA3G and showed that SMEA3G might be a potential tumor suppressor and favorable prognostic biomarker in KIRC." (PMID 38070142, 2023). "Surprisingly, we did not observe inhibition of tumor development following the expression of sema3G, which like sema3F binds to np2, or following expression of sema3B which binds to both of the neuropilins." (PMID 22936999, 2012). "In these tumours, SEMA3B, SEMA3G and NRP2 expressions were related to prolonged survival." (PMID 18781179, 2008). "In addition, it was observed that sema3G can inhibit dermal lymphangiogenesis but it is not known if sema3G can affect tumor lymphangiogenesis or tumor metastasis." (PMID 30696103, 2019). "For example, even though sema3G and sema3A expression did not inhibit at all the development of tumors from MDA-MB-231 and MDA-MB-435 cells respectively, they nevertheless strongly reduced the concentration of tumor associated blood vessels." (PMID 18818766, 2008).
cancer (14 papers, 2008 to 2025). A tumor composed of atypical neoplastic, often pleomorphic cells that invade other tissues. "Very interestingly, we found that SEMA3B, SEMA3D, SEMA3E, and SEMA3G genes were negatively associated with RNAss and DNAss (P < .0001), where the strongest association was observed for SEMA3G with RNAss (r = − 0.49) across cancer types." (PMID 32241267, 2020). "The results showed that TPX2 and BIRC5 were upregulated, while AGER, TEK, CLIC5, MAMDC2, EMCN, and SEMA3G were mostly downregulated in multiple cancer types." (PMID 40535574, 2025). "On the other hand, Sema3G, one of the quietest members of Sema family, has recently been studied as key regulator of immune responses in cancer." (PMID 40277760, 2025). "We provided a new entry point to find new targeted therapeutic pathways and therapeutic ideas for ccRCC, which increased our knowledge of SEMA3G regulatory involvement in signaling networks, as well as its role in cancer development." (PMID 36882799, 2023). "In this study, we firstly performed a pan-cancer expression and survival analysis for SEMA3G in multiple human malignancies." (PMID 38070142, 2023). "Afterward, we performed transwell assays and wound healing experiment, and discovered that cancer cell migration and invasion were significantly reduced following SEMA3G overexpression." (PMID 36882799, 2023). "Recently, although the function and immune correlation of semaphorin 3G (SEMA3G) in cancer draw more and more attention, its specific role and mechanism in KIRC are still not fully understood." (PMID 38070142, 2023). "In this study, we firstly determined the expression levels and prognostic values of SEMA3G in multiple human malignancies by integration of TCGA and GTEx cancer and normal expression and survival data." (PMID 38070142, 2023). "However, when miR-146b-5p and SEMA3G were overexpressed at the same time, migratory and invasive abilities of cancer cells were considerably increased in contrast to those with SEMA3G overexpression alone." (PMID 36882799, 2023). "However, in LIHC, SEMA3G expression in cancer tissues was markedly increased when compared with normal tissues." (PMID 38070142, 2023). "EDA, SEMA3G, ENPP5, EMX2, and OPCML were favorable factors and had low expression levels in ccRCC tissues, whereas PCDHGC3 was a risk factor and highly expressed in cancer tissues." (PMID 36505496, 2022). "We found that SEMA3B, SEMA3D, SEMA3E, and SEMA3G were all negatively associated with cancer-stem like features, but SEMA3A, SEMA3C, and SEMA3F were positively correlated with DNAss, which indicates that SEMA3s may associate with cancer cell sensitivity or resistance to chemotherapy treatment." (PMID 32241267, 2020). "One cluster includes SEMA3D, SEMA3E, SEMA3G and PLXNA4, which all showed primarily down-regulation in the tested cancer tumors." (PMID 32640719, 2020). "SEMA3A, SEMA3D, and SEMA3E showed relatively lower level of expression averaged across all cancer types compared to the rest of the SEMA3 family members.i.e., SEMA3B, SEMA3C, SEMA3F and SEMA3G, where SEMA3F had the highest expression." (PMID 32241267, 2020).
infection (1 paper, 2020). The state of being infected such as from the introduction of a foreign agent such as serum, vaccine, antigenic substance or organism. "For example, we found a novel miRNA (MLUGD00000002094 in our annotation; predicted by mirDeep2) located in an intron of the protein-coding gene SEMA3G, significantly down-regulated (log2 fc = –2.56) during Clone 13 infection." (PMID 32289119, 2020).
kidney diseases (1 paper, 2022). "We identified six genes enriched to kidney diseases and ccRCC (AR, DPP6, GNB3, IL4, SAA1, SEMA3G)." (PMID 35565241, 2022).
SEMA3G also shares sentences with these, for which no sentence is quoted: abortion (1 paper); bipolar disorder (1); glioblastoma (1); iron deficiency (1); ischemic stroke (1); lung carcinoma (1); metastatic cancer (1); metastatic tumors (1); neurodegenerative disease (1); ovarian carcinoma (1); schizophrenia (1); testicular germ cell tumor (1).